CCND2 (cyclin D2)
Diseases named in the same sentence as CCND2 in open-access papers (continued):
Sharing a sentence is not in itself a finding about the gene and the disease.
breast carcinoma (continued). "Among its dysregulated genes, CCND2 is differentially expressed between breast cancer patients with bone metastases and other patients; E2F1 can regulate DZ13 to induce a cytotoxic stress response in tumour cells metastasizing to bone; TGFB2 is related to the bone metastases development." (PMID 25163697, 2014). "Cyclin D2 is a highly conservedregulator of cyclin-dependent kinases 4 and 6 responsible for of G1/S transition.This gene is epigenetically silenced in the majority of breast cancers." (PMID 21637860, 2011). "Methylation of the cyclin D2 promoter appeared to be specific to breast cancer, however, promoter methylation of APC, RARbeta2 and RASSF1A in normal breast from breast cancer patients was associated with increased breasts cancer risk." (PMID 17362521, 2007). "Moreover, previous studies in breast cancer and Burkitt's lymphoma suggest that methylation in cyclin D2 is a tumour-specific event." (PMID 12771922, 2003). "CCND2 could be a prognostic biomarker in breast cancer, kidney renal papillary cell cancer, lung cancer, ovarian cancer, pancreatic ductal adenocarcinoma, pheochromocytoma and paraganglioma, rectum adenocarcinoma, thyroid carcinoma, and uterine corpus endometrial carcinoma (P < 0.05)." (PMID 30950241, 2019). "We also found that antroquinonol D, which is a demethylating agent and an analog of the fungal-derived Taiwanese natural product antroquinonol, could induce CCND2 mRNA and protein expression, cell cycle arrest, and migration inhibition in lung and breast cancer cell lines." (PMID 30308939, 2018). "In the present study, we observed that antroquinonol D induced CCND2 expression in breast cancer MDA-MB-231 cells, and both antroquinonol D and antroquinonol could induce CCND2 expression in lung cancer CL1-5 cells in a dose-dependent and time-dependent manner." (PMID 30308939, 2018). "In addition, CCND2 can be regulated by miR-206, miR-340, miR-154, miR-133a, miR-155, miR-1, miR-16, miR-610, miR-26a, miR-195, and miR-204, which have roles in cellular proliferation disorders (e.g., breast cancer, cervical carcinoma, and retinoblastoma)." (PMID 29662889, 2018). "To our knowledge, we are the first to show, using resources from a population-based follow-up study, that promoter methylation of APC, CCND2, HIN1, and TWIST1 may modify the inverse association between prediagnostic RPA and all-cause mortality following a breast cancer diagnosis." (PMID 28222775, 2017). "EMT transcription factors such as SNAIL and ZEB2 can inhibit cell cycle transition by inhibiting the transcription of CCND2 and CCND1, respectively, ZEB1 protein degradation induced by CDK4/6 inhibition blocks breast cancer metastasis." (PMID 39949984, 2025). "miR-383-3p and -5p enhanced the apoptosis and UV sensitivity of breast cancer cells, and their radiation targets CRYAB, CCND2, GATA3, NUCKS1, MAP3K20, and MDM2 were identified, while ATR is targeted by miR-383-5p." (PMID 37569824, 2023). "FBXL8 downregulation increased accumulation of CCND2 and IRF5 and reduced the cancer-promoting chemokines, modulated TME, leading to repressing tumor metastasis in breast cancer." (PMID 36733484, 2023). "We also found that PCK2 promoted cell cycle progression, particularly the G1/S transition, and induced upregulation of E2F1, cyclin D1, cyclin D2, and CDK4 in ER+ breast cancer cells." (PMID 35757841, 2023). "Our data suggest that TP63, YWHAZ, BRCA1, CCND2, YWHAG, and HIPK2 can be potential genetic markers of prognostic assessment, immune infiltration and chemotherapeutic drug sensitivity in breast cancer patients." (PMID 36673982, 2023). "Several previous reports have shown that treatment of breast cancer cell lines with FGFR inhibitors downregulates CCND1 and CCND2 expression and inhibits CCND/CDK4 activity, resulting in decreased pRB phosphorylation." (PMID 35884537, 2022).
breast carcinoma (continued). "We found that eight cyclins (CCNA2, CCNB1, CCNB2, CCND2, CCNE1, CCNE2, CCNF, CCNO) were differentially expressed between breast cancer and normal tissue samples, with the cut-off criterion of log2(fold change) >1, p < 0.05." (PMID 33791304, 2021). "In breast cancer, ETV4 down-regulates the expression of the cyclin D2 gene and up-regulates the expression of the cyclin D3 gene to promote cell proliferation." (PMID 34736492, 2021). "We identified 4 mRNAs (TPD52, BTG2, CCND2, LIFR) involved in the prognosis of breast cancer using survival analysis." (PMID 34545330, 2021). "Toward the same direction, another study has evaluated the prognostic significance of promoter methylation of seven genes (APC, BRCA1, CCND2, FOXA1, PSAT1, RASSF1A, and SCGB3A1) in primary tissues and cfDNA of breast cancer patients." (PMID 33942482, 2021). "The CpG methylation status of breast cancer related genes (BRCA1, CDH1, PTEN, and CCND2) is also increased." (PMID 33330580, 2020). "Another antibody array study revealed that cyclin D2, cytokeratin 18, cyclin B1, hnRNP m3-m4 and the monophosphorylated ERK were decreased in a doxorubicin resistant breast cancer cell line in comparison to a sensitive one." (PMID 31014274, 2019). "In the present study, we found that the improved survival after breast cancer with high RPA was greatest among patients with methylated APC, CCND2, HIN1, and TWIST1 promoters." (PMID 28222775, 2017). "With the exception of CCND2 and DAPK1, the genes were not only frequently methylated in the tumors but also in the corresponding tumor-adjacent and tumor-distant tissues of the breast cancer patients." (PMID 26370119, 2015). "CCND2, DAPK1, GSTP1, HIN-1, MGMT and RASSF1A were selected because they have previously been reported to be frequently methylated in primary breast cancers." (PMID 26370119, 2015). "MS-HRM analysis was carried out to determine the methylation status of CCND2, DAPK1, GSTP1, HIN-1, MGMT and RASSF1A promoters in tumor tissues and histologically normal-appearing tumor-adjacent and tumor-distant tissues of 17 breast cancer patients." (PMID 26370119, 2015). "A miR-191 dependent repression of protein level was shown for NDST1 in MGC803s, CDK6 and SATB1 in human epidermal keratinocytes, and CCND2, CSDA, and EGR1 in the human breast cancer cell line MDA-MB-231." (PMID 25992613, 2015). "For breast cancer, methylation has been noted in genes including BRCA1, p16, E-cadherin, H-cadherin, ATM, CST6, cyclin D2, PTEN, RASSF1A, APC, RARb2, GSTP1, ER, PR, as well as numerous other genes related to multiple pathways relevant for carcinogenesis." (PMID 24368439, 2014). "On the other hand, 5 genes were differentially expressed with significant difference between the breast cancer patients and carriers, BRCA1 (p = 0.03), BIRC5 (p = 0.035), CCND2 (p0.034), ATM (p = 0.012) and IGF1R (p = 0.025)." (PMID 25403427, 2014). "miR-26a was reported to directly mediate the cyclin E2 and cyclin D2 functions in HCC and breast cancer." (PMID 24116110, 2013). "Expression levels of BDNF and BDNF-correlated genes CCND2, DUSP6, EGR1, KLF10 and PTPRF are altered in breast cancer." (PMID 19737418, 2009). "In breast cancer, NGR1 can regulate the expression of CCND2 and YBX3 to inhibit breast cancer angiogenesis and slow down the progression of breast cancer, but NGR1’s ferroptosis-associated neighborhood has not been reported." (PMID 38885076, 2024). "When analyzing breast cancer tumors, including IDCs and ILCs, we observed new mutations in CDKN2A, RB1, CCND2, and CCND3 in the brain metastases of four IDCs, but not in their primary tumor counterparts." (PMID 36507516, 2022). "Moreover, hypermethylation of Cyclin D2, RAR-beta, Twist, RASSF1A, and HIN-1 genes was significantly increase in distant metastases compared with their primary site of breast cancer." (PMID 33369461, 2020).
breast carcinoma (continued). "CCND2 interacts with the phosphorylation of the tumor-suppressing retinoblastoma protein Rb, and it is also a target in TNBC, as the CpG loci are differentially methylated in various breast cancer tumor subtypes." (PMID 31921385, 2019). "The weakness of this study is the cohort of 93 samples of Taiwanese breast cancer patients were analyzed for methylation of CCND2 gene is not the same with the cohort of 18 patients were analyzed in patients’ plasma circulating cell free DNA." (PMID 30308939, 2018). "Analysis of the Infinium Human Methylation 450K BeadChip assay data from TCGA revealed that CCND2 promoter hypermethylation was more frequently aberrant in breast cancer, lung adenocarcinoma, and liver cancer than in adjacent normal tissues." (PMID 30308939, 2018). "In accord with these results, breast cancer gene array profiling indicated that elevated expression of KLF4 in both MCF10A and MCF7 breast cancer cell lines upregulates transcription of several oncogenes and cell cycle activators such as MAPK, EGF/EGFR, IGF1, CYCLIN D2, CDK1, and CYCLIN E1." (PMID 30613353, 2018). "Additionally, TiHo-0906 cells at low and high passage also displayed CNGs in regions harbouring other known breast cancer-related genes like FOXO3 and MYB (FCA B2), AKT1 (FCA B3), and GATA-3, CCND2, CDK4 and PFDN5 (FCA B4)." (PMID 30185896, 2018). "In a previous study, we determined the promoter methylation status of six tumor suppressor genes (CCND2, DAPK1, GSTP1, HIN-1, MGMT and RASSF1A) in tumor, tumor-adjacent and tumor-distant tissues from breast cancer patients and normal breast tissues from healthy controls." (PMID 28403857, 2017). "The exact roles of CCND2 and TWIST1 in breast cancer are unresolved." (PMID 28222775, 2017). "CCND2 and ESR1 are signature genes that are frequently methylated in breast cancer." (PMID 24586797, 2014). "We next focused our attention exclusively on SATB1, CCND2 and FSCN1 as mediators of miR-191 and miR-425 effects, respectively, because of their strong repression obtained after miRNA expression and their reported tumorigenic function in breast cancer." (PMID 23505378, 2013). "The aim of the current study was to analyze the involvement of methyl-CpG binding proteins (MBDs) and histone modifications on the regulation of CD44, Cyclin D2, GLIPR1 and PTEN in different cellular contexts such as the prostate cancer cells DU145 and LNCaP, and the breast cancer cells MCF-7." (PMID 20565761, 2010). "On the other hand, cyclin D2 mRNA and protein were absent in breast cancer cell lines and primary cancer tissues, while in normal breast epithelial cells, cyclin D2 was abundantly expressed." (PMID 16012517, 2005). "Several studies have indicated that methylation of cyclin D2 and its mRNA and protein were absent in most breast cancer cell lines examined and in primary breast cancers although normal breast epithelial cells had abundant expression." (PMID 15574200, 2004). "The downregulation of SEI-1, cyclin D2, and histone deacetylase 3 suggested that in addition to the identified effects of SFN against breast cancer prevention, it may also exert antitumor activities in established breast cancer cells." (PMID 31084542, 2019). "Notably, almost no methylation was observed in several CpG sites of the CCND2 promoter regions of adjacent normal tissues in all types of cancer, but hypermethylation was observed in breast cancer and lung adenocarcinoma." (PMID 30308939, 2018). "Furthermore, enforced expression of the miR-191/425 cluster in aggressive breast cancer cells altered global gene expression profiles and enabled us to identify important tumor promoting genes, including SATB1, CCND2, and FSCN1, as targets of miR-191 and miR-425." (PMID 23505378, 2013).
breast carcinoma (continued). "In addition, MCF-7 breast cancer cells accumulated in the G1 phase upon the KD of TRPC1, which was also found in the thyroid cancer cell line ML-1, where the expression of the CDK6, Cyclin D2, and D3 decreased, and the expression of their regulating inhibitor p21 increased." (PMID 35887266, 2022). "We then examined the relationship between gene amplification and genome doubling in breast cancer, by comparing CCNE1, CCNE2, CCND1 and CCND2 gene amplification in non-genome doubled and genome doubled tumours." (PMID 32823571, 2020). "However, whether detecting the aberrant methylation of CCND2 in the blood samples of patients can be applied as a noninvasive analytical method for early diagnosis, prognosis, or precision medicine in breast cancer and lung cancer patients is worth further massive screening and investigation." (PMID 30308939, 2018). "DNA promoter methylation of a gene panel including APC, CCND2, RARB, RASSF1A, and SCGB3A1 in breast cancer samples was not correlated with age in a previous study." (PMID 27028854, 2016).
prostate carcinoma (48 papers, 2005 to 2025). A carcinoma that arises from epithelial cells of the prostate gland. "Cyclin D2 is a regulatory factor of the cell cycle and hypermethylation of its promoter is associated with prostate cancer progression." (PMID 36776295, 2023). "The loss of Cyclin D2 expression is associated with BC evolution, and poor prognosis of prostate cancer." (PMID 31107884, 2019). "This is in agreement with the eQTL analysis indicating a strong association of the allele A at rs3217869 with decreased transcript levels of CCND2, a potential tumor suppressive gene in prostate cancer and strongly implicating tumor progression." (PMID 28674394, 2017). "We identified several loci including rs3217869/CCND2 within the pathway shown to be significantly associated with aggressive prostate cancer." (PMID 28674394, 2017). "This is in line with our eQTL analysis that the risk allele A at rs3217869 is significantly associated with CCND2 downregulation, indicating a potential causal role of CCND2 underlying prostate cancer susceptibility and severity." (PMID 28674394, 2017). "Among these analyses, CCND2 indicates the most prominent association with aggressive prostate cancer, supporting CCND2 as the most plausible causative gene through our integrated genetic association, follow-up eQTL and functional studies." (PMID 28674394, 2017). "Whereas some loci and genes were defined, only one SNP (rs3217869 in CCND2) was reproducibly identified to be significantly associated with aggressive prostate cancer by multiple testing." (PMID 28674394, 2017). "Together, we have identified an association of genetic variants and genes in the RTK/ERK pathway with prostate cancer aggressiveness, and highlighted the potential importance of CCND2 in prostate cancer susceptibility and tumor progression to metastasis." (PMID 28674394, 2017). "One is rs3217869 in CCND2 that was discovered by various model analyses, and suggested to be a risk factor (rs3217869 A allele) for aggressive prostate cancer." (PMID 28674394, 2017). "This analysis revealed a strong association of the risk allele A at rs3217869 with lower mRNA levels of CCND2 but not with other genes within 2 Mb of rs3217869, suggesting that CCND2 is a plausible causative gene for aggressive prostate cancer." (PMID 28674394, 2017). "The interaction term of CCND2*HSPB1 was added to the model because combined methylation of both genes together was negatively associated with death from prostate cancer." (PMID 27708246, 2016). "High DNA methylation levels of CCND2 cause deregulation of the G1/S checkpoint and correlate with clinicopathological features of tumor aggressiveness in breast and types of prostate cancer." (PMID 24932297, 2014). "In fact, methylation of cyclin D2 resulting in loss of its expression has been reported in breast, pancreatic and prostate cancer." (PMID 23786849, 2013). "High DNA methylation levels of Cyclin D2 cause deregulation of the G1/S checkpoint, and correlate with clinicopathologic features of tumour aggressiveness in breast and prostate cancer." (PMID 20565761, 2010). "This analysis revealed that loss of CCND2 expression appeared to be in aggressive prostate cancer." (PMID 28674394, 2017). "In addition, we observed a marginal association of three genes including CCND2 with aggressive prostate cancer." (PMID 28674394, 2017). "Similarly to HSPB1, CCND2 methylation displayed an HR of 0.86 [95% CI 0.75-0.98] indicating that higher levels of methylation were associated to lower risk of prostate cancer death, consistent with the role of activated CCND2 as an oncogene." (PMID 25193387, 2014). "In addition, a striking downregulation of CCND2 observed in this study may be partially explained by a previous report of promoter methylation of CCND2 in prostate cancer and its association with clinicopathological features of poor prognosis." (PMID 28674394, 2017).